NR2F6 (nuclear receptor subfamily 2 group F member 6)
Diseases named in the same sentence as NR2F6 in open-access papers (continued):
Sharing a sentence is not in itself a finding about the gene and the disease.
tumor (continued). "Data generated from tumor-bearing NR2F-deficient mice that showed reduced tumor growth caused by their hyperactive tumor immunity indicate the key function of NR2F6 as a negative intracellular regulator of the T cell immune response and as a potential target to restore anti-tumor immunity." (PMID 34948104, 2021). "Thus, therapies targeting NR2F6, once available, may help boost a localized effector T cell response at the tumor site with fewer systemic irAE." (PMID 34073258, 2021). "Nevertheless, continued research on the orphan nuclear receptor NR2F6 represents a suitable path for drug discovery and might offer an innovative, mechanism-based, therapeutic strategy to augment the sensitivity of tumor-infiltrating T cells to tumor antigens in cancer patients." (PMID 34073258, 2021). "Secondly, targeting the NR2F6 pathway using small-molecule inhibitors known to easily diffuse into the center of solid tumor masses may enable re-activation of exhausted T cells at the NSCLC tumor site." (PMID 34073258, 2021). "Furthermore, the inhibition of NR2F6 in tumor cells might also result in less survivability, proliferation and metastasis of the tumor cell." (PMID 34073258, 2021). "However, restoration of NR2F6 rescued circRHOT1-deletion-mediated inhibition on tumor growth." (PMID 31324186, 2019). "Ablation of NR2F6 enhances the expression of interleukin-2 (IL-2), interferon -γ (IFN-γ), and tumor necrosis factor-α (TNF-α) secretion, thereby promoting anti-tumor immune responses." (PMID 40424451, 2025). "Nuclear receptors RORa, NR2F6 and HNF4G are uncovered as candidate transcriptional drivers of these cells whilst closure of binding sites for E2F2 and E2F4 indicate post-treated tumour having low proliferative capacity." (PMID 39341888, 2024). "Recently, we showed that inhibition of NR2F6 gene function improves CD4+ and CD8+ T cell infiltration in addition to effector functions at the tumor site in different mouse tumor models." (PMID 34073258, 2021). "CRISPR-mediated Nr2f6 ablation in combination with PD-L1 blockade in tumors resistant to anti-PD-L1 monotherapy has been able to increase IFN-γ secretion and delay tumor growth, suggesting a synergistic effect." (PMID 34446084, 2021). "The higher NR2F6 expression in these lymphocytes correlated with a higher PD-1 and CTLA-4 expression in the lymphocytes, as well as PD-L1 expression in tumor cells." (PMID 32752295, 2020). "Heterozygous Nr2f6+/− mice showed significant better survival after tumor challenge with both B16 and MC38 cell lines similar to homozygous Nr2f6−/−mice." (PMID 29670099, 2018). "To evaluate the effect of partial versus complete Nr2f6-deficiency on tumor growth suppression, we injected wild-type Nr2f6+/+, heterozygous Nr2f6+/− and knockout Nr2f6−/− mice with either B16-OVA or MC38 tumor cells and monitored tumor growth." (PMID 29670099, 2018). "This suggests that targeting the immune checkpoint NR2F6 in those presumably tumor antigen-reactive but probably exhausted T-cell clones in the patient group with NR2F6positive TILs may result in increased anti-tumor effector responses during an envisioned NR2F6-targeted therapy." (PMID 29670099, 2018). "In the absence of NR2F6, bone marrow-derived, peripheral, tumor-infiltrating, and in vitro expanded NK cells express significantly enhanced levels of the activating receptor NKp46." (PMID 39920136, 2025). "NR2F6 is commonly expressed in resting T cells at low levels; however, it is highly inducible in effector (but not regulatory) T cells in the inflammatory tumor microenvironment." (PMID 40424451, 2025). "NR2F6 gene ablation/PTT-mediated aPD-L1 immune-enhancing approach allows local treatment-stimulated immune responses to build long-term immune memories throughout the body, thereby inhibiting tumor metastasis." (PMID 40424451, 2025). "Re-expression of NR2F6 in the absence of circMIRO1 rescued growth, migration, invasion, and tumor growth in vivo." (PMID 39128718, 2024).
tumor (continued). "The OE of NR2F6 WT did not promote tumor growth, while NR2F6 DNA binding mutant (MT) attenuated tumor growth." (PMID 37406115, 2023). "Noting that the degree of tumor growth inhibition did not coincide with the efficiency of NR2F6 KD, we set to confirm these observations by an independent genetic approach." (PMID 37406115, 2023). "S2, M and N), suggesting that NR2F6 transcriptional activity is required, but ectopic OE of NR2F6 only is not sufficient to accelerate tumor growth." (PMID 37406115, 2023). "Thus, the ablation of genetic NR2F6 strongly enhances the secretion of interleukin-2 (IL-2), interferon-γ (IFN-γ), and tumor necrosis factor-α (TNF-α) both at tumor sites and ex vivo, thereby promoting antitumor immunological responses." (PMID 35907841, 2022). "NR2F6 has been defined as a negative master switch of both central nervous system inflammation, on the one hand, and anti-tumour responses, on the other." (PMID 31937317, 2020). "Furthermore, we examined the expression of NR2F6 in 100 paired HCC samples and found that NR2F6 was upregulated in tumor tissues." (PMID 31324186, 2019). "Notably, however, the number of NR2F6-expressing TILs was highly correlated to the abundance of PD-1 and CTLA-4-expressing TIL as well as PD-L1 expression on tumor cells." (PMID 29670099, 2018). "We could show a significantly enhanced tumor outgrowth in Nr2f6−/− mice treated with a combination of CD4+ and CD8+ depleting antibodies when compared to the IgG2b-treated Nr2f6−/− control group." (PMID 29670099, 2018). "To confirm the importance of NR2F6 as T-cell-intrinsic suppressor of T-cell-mediated tumor growth control in vivo, we next employed ex vivo siRNA-mediated Nr2f6 silencing prior ACT of autologous T cells into a MC38 subcutaneous mouse tumor model." (PMID 29670099, 2018). "A more detailed survival study showed that shorter OS and high NR2F6 expression were significantly correlated in the no tumor recurrence subgroup." (PMID 27775588, 2016). "Furthermore, IHC showed a significant positive correlation between NR2F6 expression and FIGO stage, SCC antigen, tumor recurrence, vital status, chemotherapy, and LNM." (PMID 27775588, 2016). "Collectively, we can speculate that, on the one hand, NR2F6 functions as a nonimmunological regulator: expressed in cancer, facilitating angiogenesis and tumor invasion." (PMID 37575237, 2023). "In this perspective review, the role of NR2F6 as an emerging and druggable target in immuno-oncology research will be discussed, with special emphasis on the unique potential of NR2F6 and its critical and non-redundant role in both immune and tumor cells." (PMID 34073258, 2021). "Thus, combining adoptive transfer of Nr2f6 CRISPR/Cas9 genetically modified T cells showed synergistic effects with both the established PD-L1 and the CTLA-4 checkpoint blockade to promote tumor regression and increase survival in a subcutaneous tumor mouse model." (PMID 31937317, 2020). "Additionally, as long as we do not know the exact functions of NR2F6 in cancer cells, the different expression patterns are an indicator of a different tumor biology." (PMID 32752295, 2020). "Taken together, this data suggest that disruption of lymphatic Nr2f6 converts tumor-infiltrating T cells into IFNγ- and IL-2-hypersecreting effector cells, apparently sufficient to prime the TIME for immune checkpoint therapy to more effectively control tumor growth." (PMID 31937317, 2020). "Importantly, these tumor growth effects depend primarily on NR2F6 function in both CD4+ and CD8+ effector (but not regulatory) T-cell subsets." (PMID 29670099, 2018). "As expected, tumor growth in Nr2f6−/− mice was significantly reduced and tumors exhibited significantly increased numbers of tumor-infiltrating CD45+CD3+ T cells when compared to wild-type animals, calculated at the level of total numbers on a tumor size basis." (PMID 29670099, 2018).
tumor (continued). "Additionally, as already mentioned, NR2F6-positive peritumoral lymphocytes which may significantly influence tumor’s microenvironment were not analyzed in this study." (PMID 36884115, 2023). "In summary, our study herein demonstrated that the CCF-mediated PTT, NR2F6 gene silencing, and aPD-L1 combination treatment generated an attractive concept in HCC therapy that could stimulate effective synergistic therapeutic immunotherapy to inhibit tumor growth." (PMID 35907841, 2022). "Furthermore, NR2F6 is ubiquitously expressed and found at rather low levels in resting T cells; however, it is highly inducible in effector (but not regulatory) T cells in an inflamed tumor microenvironment." (PMID 34073258, 2021). "Besides, an upward trend of NR2F6 expression could still be observed in residual tumor when compared to an untreated group, although nonparametric t tests did not indicate a significantly statistical p-value (p = 0.057)." (PMID 34304715, 2021). "Absence of NR2F6, either through genetic ablation in Nr2f6 knockout mice or by the means of siRNA knockdowns, increases the immune system’s ability to mount effective immune responses, resulting in striking anti-tumor effects in different advanced mouse models relevant to human cancer." (PMID 29670099, 2018). "Unlike NR2F6 KO tumor-bearing mice treated with immunoglobulin G (IgG) antibodies, CD8+ T cell depletion abolished tumor growth inhibition and decreased survival of mice harboring NR2F6 KO B16F10 tumors." (PMID 37406115, 2023). "The fraction of cells carrying the exhaustion markers Lag-3, Tim-3, or PD-1 was comparable between Nr2f6+/+ and Nr2f6−/− CD8+OVAtet+ T cells, indicating that Nr2f6−/− cells do not become excessively exhausted 26, which is in contrasting our previous observations in tumor-infiltrating T cells." (PMID 33589606, 2021).
cancer (33 papers, 2009 to 2025). A tumor composed of atypical neoplastic, often pleomorphic cells that invade other tissues. "Based on the CIBERSORT method, we observed that NR2F6 expression was significantly associated with 22 classes of immune cell infiltration in 44 cancer types." (PMID 40424451, 2025). "In Nr2f6‐deficient mice, cancer outgrowth is reduced due to increased T‐cell infiltration and T‐cell effector functions, including secretion of IL‐2 and IFNγ." (PMID 32246891, 2020). "In most of these cancers, a higher NR2F6 expression was associated with a poor prognosis." (PMID 32752295, 2020). "Therefore, we suggested that elevated NKp46 expression could still enhance antitumor NK cell responses in Nr2f6-deficient mice during cancer progression." (PMID 39920136, 2025). "In light of this, we focused on investigating the role of the orphan nuclear receptor NR2F6 in retroperitoneal NB, validating its potential as a prognostic factor and its significance in cancer development." (PMID 40424451, 2025). "Small molecule modulation of NR2F6 activitymight therefore be a novel strategy in cancer treatment, benefitingfrom this dual role of NR2F6." (PMID 40931005, 2025). "In this study, we comprehensively explored the expression of NR2F6 in 34 human cancers based on TCGA, TARGET, and GTEx analysis databases." (PMID 40424451, 2025). "We analyzed the relationship between NR2F6 expression and immune regulatory genes in different cancer types." (PMID 40424451, 2025). "To address this gap, we conducted gene expression difference analysis using data from 34 cancer-related sources in the UCSC database, revealing a significant up-regulation of NR2F6 in various cancers." (PMID 40424451, 2025). "Our study thoroughly explored NR2F6 expression in cancer and normal tissues, highlighting significant differences and discussing its potential as a predictive marker." (PMID 40424451, 2025). "Our results showed that NR2F6 expression was significantly upregulated in human cancers relative to adjacent normal tissues." (PMID 40424451, 2025). "By analyzing the expression of 26 cancer types, we observed significant differences in NR2F6 expression levels in four tumors (ESCA, BLCA, ACC, KICH) in different clinical stages." (PMID 40424451, 2025). "Another research show that NR2F6 is vital for immune surveillance in cancer and poor chemotherapy survival." (PMID 38717954, 2024). "NR2F2 and NR2F6 are members of the nuclear receptor (NR) superfamily that has been a source of therapeutic targets for the treatment of several diseases, including cancers." (PMID 37370765, 2023). "The current study, which takes advantage of large population databases and systematic data analysis and shows promising transcriptional findings, provides novel insights regarding the involvement of the NR2F6 pathway in immune responses and cancer development." (PMID 37575237, 2023). "The inhibition of immune checkpoint protein NR2F6 showed promising results in both pre-clinical cancer therapy in vivo and human peripheral blood mononuclear cells (PBMC) in vitro models." (PMID 37370765, 2023). "Nuclear receptor subfamily 2 group F member 6 (NR2F6) is a promising checkpoint target for cancer immunotherapy." (PMID 37575237, 2023). "The targeting of NR2F6 for cancer immunotherapy has the potential to increase the response rates of cancer patients and/or to extend treatment to a broader range of cancer types." (PMID 38005965, 2023). "The aim of this study is the exploration of the orphan nuclear receptor NR2F6 aiming a contribution to future, immune-guided cancer treatment." (PMID 36884115, 2023). "Nuclear receptor subfamily 2, group F, member 6 (NR2F6) acts as an intracellular immune checkpoint in T cells and plays a negative regulatory role in T cell activation in cancer." (PMID 35907841, 2022). "Mechanistically, the EAE and cancer effects are at least partly due to NR2F6 suppression of nuclear factor of activated T cells (NFAT) activity by competitive DNA binding." (PMID 36052079, 2022).
cancer (continued). "This double score principle, which targets NR2F6 in cancer patients, is intended to improve the effectiveness and expand the applicability of cancer immunotherapies and thus enable patients to survive longer." (PMID 34073258, 2021). "Additional work needs to be done to evaluate precisely how IFN-γ in the context of NR2F6 regulates cell migration, intracellular signaling, and effector memory responses in infectious diseases and cancer." (PMID 33589606, 2021). "NR2F6, a member of nuclear receptors, has been suggested to play a crucial role in several human cancers." (PMID 34304715, 2021). "Here, we discuss the unique potential of NR2F6 as an emerging target for cancer immunotherapy to significantly increase response rates of cancer patients and/or to extend treatment to a broader range of cancer types." (PMID 34073258, 2021). "Both NR2F6 knockdown, GSI, and Notch3 knockdown helped to overcome cisplatin resistance in NR2F6-overexpressing cancer stem cells." (PMID 34680255, 2021). "NR2F6 has been proposed as an alternative cancer immune checkpoint in the effector T cell compartment." (PMID 31937317, 2020). "The physiological relevance of NR2F6 function in clinically relevant cancer models as well as in T cell biology has been firmly established." (PMID 31937317, 2020). "Employing a robust sgRNA transfection-based knockout system into primary mouse T cells from Cas9 transgenic mice, efficient CRISPR-mediated Nr2f6 gene editing for cancer immunotherapeutic purpose has been established." (PMID 31937317, 2020). "NR2F6 was only expressed in the cancer cells, but there was still a significantly higher expression in the PTs with immune cell infiltration." (PMID 32752295, 2020). "As a pre-clinical proof of concept, this establishes NR2F6 as a promising cancer therapeutic candidate target and NR2F6 inhibition as a sensitizing concept for next-generation immune-oncology regimens." (PMID 31937317, 2020). "Because T lymphocyte-intrinsic NR2F6 acts as a potent and selective repressor of effective cancer immunity, NR2F6 appears to represent a crucial regulator of cancer immune tolerance induction and maintenance." (PMID 29670099, 2018). "Taken together, targeting the NR2F6 pathway is a mechanistically independent option in cancer treatment regimens and identifies a candidate role of the orphan nuclear receptor NR2F6 in governing effector T-cell function relevant for cancer cell rejection." (PMID 29670099, 2018). "Our data define NR2F6 as an intracellular immune checkpoint that suppresses adaptive anti-cancer immune responses and set the stage for clinical validation of targeting NR2F6 for next-generation immuno-oncological regimens." (PMID 29670099, 2018). "With current studies demonstrating increased expression of NR2F6 in multiple cancer types, targeting NR2F6 could serve as an independent and potentially synergistic option." (PMID 40424451, 2025). "Together with our pancancer analysis, these results suggest that NR2F6 may serve as a potential marker for poor prognosis in different cancers, further indicating its involvement in cancer progression." (PMID 40424451, 2025). "Overall, NR2F6 plays a crucial role in cellular homeostasis and various diseases, including cancer." (PMID 37575237, 2023). "Interestingly, genetic knockout of NR2F6 significantly improves responses to PD-1/PDL-1 cancer immune checkpoint inhibition." (PMID 37575237, 2023). "However, the knowledge on the role and function of NR2F6 as a suppressor of immune response in cancer is currently limited and the fate of NR2F6-based therapy depends on the outcome of clinical trials." (PMID 37370765, 2023). "Furthermore, the chemosensitivity of NR2F6-positive carcinomas seems to be different to NR2F6-negative carcinomas." (PMID 36884115, 2023). "Several studies have shown that NR2F6 overexpression may lead to a certain chemotherapy resistance of different carcinomas." (PMID 36884115, 2023).